CHI3L1 (chitinase 3 like 1)
Diseases named in the same sentence as CHI3L1 in open-access papers (continued):
Sharing a sentence is not in itself a finding about the gene and the disease.
liver fibrosis (continued). "CHI3L1, a member of the chitosanase family, is highly expressed in liver tissues, can be secreted into the ECM of the liver, and is highly expressed in hepatic fibrosis." (PMID 38962736, 2024). "Treatment with DAAs significantly and sustainably improved hepatic fibrosis in patients with CHC, with serum CHI3L1 levels being significantly lower at the end of treatment compared baseline levels." (PMID 38962736, 2024). "Additionally, CHI3L1 is involved in innate immune system and ECM remodeling and is associated with chronic viral hepatitis, alcoholic hepatitis, NAFLD, and other chronic liver diseases, with a close association between the degree of liver fibrosis and ECM synthesis." (PMID 38962736, 2024). "By studying the levels of five serum liver fibrosis markers in OSA patients, a novel marker—CHI3L1—was found, and detecting CHI3L1 content in serum is safer and faster than detecting other markers." (PMID 38003338, 2023). "In the present study, we investigated changes in the levels of five serum liver fibrosis markers in patients with OSA and found that serum HA, CIV and CHI3L1 levels were significantly increased in patients with compared with healthy volunteers." (PMID 35280860, 2022). "Specifically, serum liver fibrosis markers HA, CIV and CHI3L1 levels were positively correlated with apnea-hypopnea index (AHI), but negatively correlated with the lowest saturation oxygen (LSaO2) respectively." (PMID 35280860, 2022). "Wang et al24 demonstrated that CHI3L1 is not only a noninvasive marker for assessing liver fibrosis before treatment in CHB patients, but also a potential marker for monitoring liver fibrosis changes during treatment." (PMID 31916309, 2020). "CHI3L1 can promote hepatic stellate cell (HSC) activation and proliferation, therefore directly participating in the formation and maintenance of hepatic fibrosis." (PMID 33082884, 2020). "In conclusion, our study revealed a significant elevation in serum CHI3L1 concentration among patients with AILDs-related liver fibrosis compared to those without fibrosis." (PMID 40352927, 2025). "Some studies suggest that CHI3L1 inhibits hepatic macrophage apoptosis by suppressing Fas expression and activating the PI3K/Akt signaling pathway, leading to the accumulation and activation of liver macrophages and exacerbating liver fibrosis." (PMID 40352927, 2025). "The CHI3L1 concentrations did not change significantly with increasing liver fibrosis stages (P=0.767), nor did the FIB-4(P=0.068) and APRI (P=0.055) indices." (PMID 38304922, 2024). "Little is known concerning the progression of hepatic fibrosis after HCV eradication; however, recent studies have suggested that serum CHI3L1 levels may be a non-invasive marker for monitoring fibrosis in patients with CHC." (PMID 38962736, 2024). "Although a direct correlation between CHI3L1 serum concentrations and liver fibrosis stages has been well established in NAFLD, the mechanisms by which CHI3L1 contributes to the progression of NASH and liver fibrosis remain incompletely understood." (PMID 37166517, 2023). "Circulating levels of CHI3L1 (YKL-40) have been proposed as a robust non-invasive biomarker of liver fibrosis that allows for staging and diagnosis of fibrosis without the need of a liver biopsy." (PMID 37166517, 2023). "The results of ANOVA analysis showed a statistically significant difference in the indicators of different hepatic fibrosis stages (all P < 0.05), except for CHI3L1 that was not statistically significant." (PMID 36245721, 2022). "Our team’s previous research has indicated that serum CHI3L1 levels increase with the progression of liver fibrosis in chronic hepatitis B (CHB) patients and outperform Hyaluronic acid (HA), type III procollagen III (PC-III), type IV collagen IV (IV-C), and laminin (LN) in diagnosing liver fibrosis." (PMID 40352927, 2025).
liver fibrosis (continued). "CHI3L1 concentrations did not change significantly with the increase in liver fibrosis stages, nor did the FIB-4 and APRI indices, and all three showed poor diagnostic value for liver fibrosis." (PMID 38304922, 2024). "However, serum CHI3L1, FIB-4, and APRI were recommended indicators to assess liver fibrosis." (PMID 38304922, 2024). "Elevated circulating levels of CHI3L1 have been observed in chronic inflammatory states such as RA, osteoarthritis (OA), inflammatory bowel disease (IBS), systemic lupus erythematosus (SLE), lichen planus, sarcoidosis, hepatic fibrosis, obesity, and other conditions." (PMID 37834128, 2023). "However, CHI3L1 levels did not change significantly with the increase in liver fibrosis stages." (PMID 38304922, 2024). "For the noncirrhotic patients, although the CHI3L1 levels at T0 were approximately 40% lower in the non-LC group than in the LC group, similar patterns of decline were observed, suggesting that DAA treatments effectively reduced liver fibrosis regardless of the cirrhosis status before treatment." (PMID 33082884, 2020).
rheumatoid arthritis (66 papers, 2007 to 2026). A chronic, systemic autoimmune disorder characterized by inflammation in the synovial membranes and articular surfaces. "Using the Open Targets Platform, we found that several cancers, neurological diseases, pulmonary diseases, cardiovascular diseases, and rheumatoid arthritis, among others, are critically associated with CHI3L1." (PMID 38177294, 2024). "Furthermore, hypomethylation of the CHI3L1 gene in rheumatoid arthritis is associated with increased expression of YKL-40." (PMID 26696093, 2015). "The present study investigates the association between single nucleotide polymorphisms (SNPs) in the chitinase 3-like 1 (CHI3L1) gene and serum concentrations of YKL-40 in Danish patients with rheumatoid arthritis (RA) and healthy controls as well as the association with RA in the Danish population." (PMID 21714862, 2011). "This study aims to elucidate the molecular regulatory mechanisms of Chitinase-3-like protein 1 (CHI3L1) in rheumatoid arthritis (RA) and its association with disease activity, focusing on its translational potential in RA diagnosis, dynamic monitoring, and precision therapy." (PMID 41488645, 2025). "CHI3L1 is strongly expressed by macrophages in inflammatory diseases, such as rheumatoid arthritis, asthma, liver cirrhosis, encephalitis, stroke, multiple sclerosis, and glioblastoma." (PMID 38177294, 2024). "In this review, we focus on the role of CHI3L1(YKL40) in pathological diseases, including rheumatoid arthritis, neurological and autoimmune diseases, and cancers." (PMID 38543093, 2024). "For example, CHI3L1 also known as YKL-40 is elevated by chronic inflammation in the context of inflammatory bowel disease, rheumatoid arthritis or cancer." (PMID 33920100, 2021). "Several studies have reported increased levels of CHI3L1 protein and/or mRNA in patients with a wide spectrum of pathologies including rheumatoid arthritis, osteoarthritis (OA), giant cell arteritis and malignancies." (PMID 29547667, 2018). "YKL-40, also known as human cartilage glycoprotein-39 or chitinase-3-like-1, is a pro-inflammatory protein that is highly expressed in rheumatoid arthritis (RA) patients." (PMID 28448439, 2017). "CHI3L1 is a candidate auto antigen in rheumatoid arthritis related to the ability of cells to respond to and cope with variations in their environment." (PMID 26978347, 2016). "Serum and SF (Synovial fluid) levels of CHI3L1 are increased in inflammatory diseases and correlate with the grade of cartilage degeneration in rheumatoid arthritis." (PMID 26978347, 2016). "In rheumatoid arthritis CHI3L1 serum levels are elevated and correlate with disease activity and progression." (PMID 24116216, 2013). "The development of other inflammatory diseases, such as rheumatoid arthritis (RA) and atopy, also involves the expression of CHI3L1." (PMID 38177294, 2024). "Kaspar et al16 analysed eight CHI3L1 SNP genotypes and YKL‐40 levels in rheumatoid arthritis and healthy individuals." (PMID 33280245, 2021). "In particular, the prophylactic effects against rheumatoid arthritis were mediated via inhibiting pro-inflammatory cytokine, alleviating oxidative stress, and down-regulating the expression of COX-2 and CHI3L1." (PMID 31747811, 2019). "Finally CHI3L1 has been proposed as a candidate autoantigen in rheumatoid arthritis (RA) due to its different expression in cartilage and synovial tissues, and to a possible link with the human leukocyte antigen (HLA)-DR4 shared epitope." (PMID 27826220, 2016). "To this end we first assessed CHI3L1 levels on sera and synovial fluids from several JIA patients and showed that they are significantly higher at the inflamed tissue when compared to the periphery, thus confirming literature data on rheumatoid arthritis." (PMID 27826220, 2016). "CHI3L1 mRNA is not detectable in normal human cartilage, though it is expressed in cartilage from patients with rheumatoid arthritis." (PMID 26978347, 2016).
atherosclerosis (58 papers, 2009 to 2025). A disease characterized by the build-up of fatty material and calcium deposition in the arterial wall resulting in partial or complete occlusion of the arterial lumen. "Recently, CHI3L1 was regarded as a pro-inflammatory and proliferation cytokine and was associated with the initiation and progress of atherosclerosis." (PMID 34349665, 2021). "Although the relationship between CHI3L1 and CAD is important, there is a controversy in the association between blood CHI3L1 levels and the severity of atherosclerosis." (PMID 24729664, 2014). "The overall association scores of CHI3L1 in coronary artery disease, peripheral arterial disease, carotid atherosclerosis, and atherosclerosis were 0.102, 0.091, 0.064, and 0.062, respectively, which are similar to the overall association scores of VCAM1 and ITGAX." (PMID 38177294, 2024). "Moreover, an augmented circulating level of Chi3l1 is also associated with a higher prevalence of hypertension and atherosclerosis." (PMID 37375598, 2023). "CHI3L1 can induce atherosclerosis in human umbilical vein endothelial cells by regulating lipopolysaccharide." (PMID 41475082, 2025). "The text-mining scores of CHI3L1 in coronary artery disease, peripheral arterial disease, carotid atherosclerosis, and atherosclerosis were 0.842, 0.750, 0.525, and 0.511, respectively." (PMID 38177294, 2024). "In patients with vascular dementia, the level of the inflammatory marker Chi3l1 is significantly higher in Helicobacter pylori (Hp)-positive patients than in Hp-negative patients, suggesting that Hp-induced inflammation may be a risk factor for atherosclerosis in patients with vascular dementia." (PMID 39769202, 2024). "Mechanistically, Chi3l1 inhibits macrophage apoptosis by upregulating Aven to suppress the activation of caspase-9 in early-stage atherosclerosis." (PMID 39769202, 2024). "Atherosclerosis is a chronic inflammatory disease, and Chi3l1 is overexpressed in patients with atherosclerosis." (PMID 39769202, 2024). "CHI3L1 plays a crucial role in vascular inflammation and atherosclerosis development by promoting EC inflammation and vascular smooth muscle cells migration and value-addition." (PMID 39026176, 2024). "Many studies have demonstrated that Chi3l1 is a reliable biomarker and promising therapeutic target for blood vessel-related inflammatory diseases such as atherosclerosis, coronary artery disease, stroke, and hypertension." (PMID 39769202, 2024). "The relationship between CHI3L1 and atherosclerosis is closely related to macrophage activation, and the enhancement of TNF-α also promotes the expression of CHI3L1 in macrophages." (PMID 38003338, 2023). "Another study showed that increased CHI3L1 expression exacerbated atherosclerosis by mediating EC inflammation and vascular smooth muscle cell (VSMC) activation." (PMID 34349665, 2021). "In this study, we demonstrated that CHI3L1 enhanced neovascularization in carotid plaques and migration and tubular formation of HUVECs, which reflected that CHI3L1 had a role in adjusting angiogenesis in atherosclerosis." (PMID 34349665, 2021). "Other studies support our conclusion that miR-342-3p is protective against atherosclerosis, as when miR-342-3p was downregulated in endothelial cells in mice, an increase in chitinase 3 like 1 (Chi3l1), a mediator of endothelial inflammation, was observed." (PMID 33003647, 2020). "The involvement of CHI3L1 in the pathogenesis of atherosclerosis and manifestation of CVD has recently been highlighted." (PMID 28319050, 2017). "The suppression of atherosclerosis in apolipoprotein E knockout mice by lentivirus-mediated CHI3L1 gene silencing suggests a role of YKL-40 on plaque progression and as a candidate therapeutic target in atherosclerosis." (PMID 25486056, 2014).
atherosclerosis (continued). "First, we investigated the correlation between CHI3L1 expression and pathogenesis of atherosclerosis by measuring the changes of CHI3L1 in the aortic tissues of patients undergoing coronary artery bypass graft (CABG) surgery." (PMID 24729664, 2014). "A study of 290 Koreans has shown significant associations between a promoter SNP of CHI3L1 (rs946261) and levels of serum LDL, a major risk factor for the development of atherosclerosis." (PMID 23071724, 2012). "CHI3L1 knockout significantly inhibits atherosclerosis development." (PMID 41475082, 2025). "CHI3L1 is therefore crucial to atherosclerosis and vascular stenosis." (PMID 41475082, 2025). "Overall, the association between CHI3L1 and these target proteins in CVD suggests that CHI3L1 plays a critical role in CVD, including atherosclerosis, and that targeting CHI3L1 may be a promising therapeutic approach for atherosclerotic vascular disease." (PMID 38177294, 2024). "Moreover, Chi3l1 can exacerbate atherosclerosis by mediating endothelial cell (EC) inflammation and vascular smooth muscle cell (VSMC) activation." (PMID 39769202, 2024). "Although the role of CHI3L1 in the pathogenesis of atherosclerotic vascular disease remains understudied, recent research findings suggest that targeting CHI3L1 may provide a novel therapeutic strategy for atherosclerosis." (PMID 38177294, 2024). "However, the pathophysiological importance of CHI3L1 for CVD, especially hypertension and atherosclerosis, and the correlation between CHI3L1 and its associated genes have not been sufficiently discussed." (PMID 38177294, 2024). "CHI3L1, CD36, IL-18, and RARRES2 genes have also been reported to be associated with IR, whereas APOA1, CD36, LEP, FN1, and CETP genes were found to be associated with atherosclerosis." (PMID 36984867, 2023). "We have identified seven genes (CHI3L1, CD36, LEPR, RETN, IL-18, RBP-4, and RARRES2) that may be associated with IR and atherosclerosis as having possible evidence based on the disease pathogenesis of ED and inflammation." (PMID 36984867, 2023). "Hence, mice with knockout of CHI3L1 and/or IL-13Rα2 will more comprehensively illuminate the role of CHI3L1 in the initiation and progression of atherosclerosis and neovascularization in atherosclerotic plaques through the IL-13Rα2 pathway." (PMID 34349665, 2021). "Given the proangiogenic role of CHI3L1 in various tumor cells, it is necessary to understand whether CHI3L1 has a similar role in adjusting tube formation of human umbilical vein ECs (HUVECs) and neovascularization in late-stage atherosclerosis." (PMID 34349665, 2021). "Moreover, the abundant expression and secretion of chitinase 3-like 1 (CHI3L1) at early stages of atherosclerosis triggers CCL2 expression in macrophages via activation of MAPK and NF-κB pathways." (PMID 26001902, 2015). "The most important point to highlight after conducting this study is that although CHI3L1 gene promoter variants showed highly significant association with YKL-40 levels, only the latter revealed a significant association with multiple atherosclerosis-related traits and the risk of PAD." (PMID 25486056, 2014). "CHI3L1 is overexpressed in aorta from patients with atherosclerosis and the lentivirus-mediated CHI3L1 gene silencing could represent a new strategy to inhibit plaques progression." (PMID 24729664, 2014). "However, further investigation is required to determine whether the attenuation of Th1 immune responses results in the dominance of Th2 responses in CHI3L1-mediated macrophage differentiation mechanisms in atherosclerosis." (PMID 38003338, 2023). "Besides IR and atherosclerosis, CHI3L1 is also involved in inflammatory processes." (PMID 36984867, 2023). "However, whether CHI3L1 prompts the angiogenesis of late atherosclerosis in animal models, as well as the concrete mechanism for CHI3L1 involved in atherosclerosis, is still unknown." (PMID 34349665, 2021).
atherosclerosis (continued). "One study investigating the role of CHI3L1 in patients with peripheral arterial disease showed that severity of atherosclerosis is associated with higher blood CHI3L1 levels, and another paper concluded that circulating CHI3L1 was not specifically related to the size of atherosclerotic stenosis." (PMID 24729664, 2014). "More importantly, silencing of CHI3L1 diminished atherosclerotic burden and increased plaque stability in ApoE−/− mice, and it might provide a new therapeutic approach to the treatment of atherosclerosis." (PMID 24729664, 2014). "Acting as a stimulus for M1 macrophages, CHI3L1′s ability to suppress TNF-α secretion is thought to mediate macrophage differentiation and contribute to atherosclerosis." (PMID 38003338, 2023). "This review focuses on the link between IR, T2DM, atherosclerosis, CAD, and the potential genetic markers CHI3L1, CD36, LEPR, RETN, IL-18, RBP-4, and RARRES2 genes." (PMID 36984867, 2023). "This review identified CHI3L1, CD36, LEPR, RETN, IL-18, RBP-4, and RARRES2 genes as the potential genetic markers of IR and atherosclerosis in T2DM patients with CAD." (PMID 36984867, 2023). "Genes such as COMP (cartilage oligomeric matrix protein), CHI3L1, PLA2G2A, P2RY12, CR1, HPSE (heparanase), PTX3 and SERPINE1 were related to atherosclerosis." (PMID 34218797, 2021). "YKL-40, previously known as chitinase-3-like protein 1 (CHI3L1), is an inflammation-related glycoprotein that promotes atherosclerosis, but its application and optimal cut-off value as a prognostic biomarker in coronary heart disease (CHD) require more clinical evidence." (PMID 38028459, 2023). "In summary, our results support the conclusion that these proteins (i.e., SPP1, ATP6V0D2, CHI3L1, and BDNF) likely play important roles in the development of atherosclerosis-related diseases and further indicate that they are potential diagnostic and therapeutic biomarkers." (PMID 31682178, 2019). "Furthermore, our study indicates that SPP1, CD36, ATP6V0D2, CHI3L1, MYH11, and BDNF, which showed favorable diagnostic performance and high correlations with several clinical biochemical parameters, may potentially serve as biomarkers to diagnose and monitor the prognosis of atherosclerosis." (PMID 31682178, 2019). "Interestingly, Trem2+ LAMs expressing Spp1 showed a transcriptional profile similar to osteoclasts during advanced stages of murine atherosclerosis, and human multinucleated giant cells express MAM markers such as SPP1, MMP9, CHI3L1 in granulomatous slack skin." (PMID 37706477, 2023).